RAB27A (RAB27A, member RAS oncogene family)
Diseases named in the same sentence as RAB27A in open-access papers (continued):
Sharing a sentence is not in itself a finding about the gene and the disease.
tumor (continued). "In addition to this cell-autonomous mechanism, Rab27a activity in 4T1 cells mediates secretion of EV and cytokines that recruit tumor-promoting neutrophils." (PMID 37770957, 2023). "Studies have revealed that blockade of RAB27A could therefore decrease the primary tumor growth by suppressing sEV secretion." (PMID 37685910, 2023). "Interestingly, we observed that mRNA expression levels of RAB27A were lower in CRC tissues compared to tumor adjacent tissues, with higher expression having favorable prognostic value." (PMID 36980570, 2023). "Several studies have demonstrated that Rab27a is critical for efficient exosomes-mediated communication modulating different cancer related processes such as cancer cells proliferation and dissemination, as well as remodeling of the tumor microenvironment." (PMID 37641131, 2023). "Interestingly, we observed a significant increase in tumor burden in the PKT Ashen (Rab27a KO) in comparison with the PKT (Rab27a WT) reflected in a significant increase in the number of liver macrometastasis in the Rab27 KO mice." (PMID 37641131, 2023). "While ectopic expression of RAB6B, or RAB27A, partially reversed the observed statin sensitivity, co-expression of RAB6B and RAB27A essentially rescued growth inhibition by statin treatment, as demonstrated using in vitro cell proliferation and in vivo tumor xenograft growth measures." (PMID 37277330, 2023). "It is also reported that RAB27A is down-regulated in CRC primary tumor tissues compared with the adjacent tissues, and down-regulation of RAB27A is associated with poor differentiation, advanced TNM stage, distant metastasis, local recurrence and poor prognosis." (PMID 36371494, 2022). "We speculate that the significant decrease in neutrophils in Rab27a-overexpressing tumor-bearing mice may be attributed to the secretory substances that reduce the number of neutrophils or inhibit neutrophil attraction." (PMID 35053535, 2022). "Therefore, we further examined tumor growth in Rab27a-overexpressing MDA-MB-231 cell xenograft mice with elevated levels of Rab27a." (PMID 35053535, 2022). "Furthermore, the lactate levels in the plasma of cancer patients were positively correlated with the HIF-1α and Rab27a proteins in tumor tissues." (PMID 36531060, 2022). "To validate the role of TEVs in this process, we performed the same experiments in the TRAMP-C2 Rab27a−/− tumor-bearing mice and found that both treatments significantly inhibited tumor growth and had comparable antitumor effects after the production of endogenous TEVs was suppressed." (PMID 36220994, 2022). "Interestingly, it seems that the function of RAB27A in tumor progression is inconsistent among different cancer types, even among different articles focusing on CRC." (PMID 36371494, 2022). "Additionally, knockdown of Rab27a inhibited tumor migration, with changes in related signaling molecules, whereas overexpression of Rab27a reversed this phenomenon." (PMID 35053535, 2022). "Similarly, in a murine model of breast cancer, Rab27A knockdown in a 4T1 cell line markedly inhibited tumor progression and enhanced anti-PD-L1 curative effect." (PMID 35090497, 2022). "Moreover, tumor B cells have increased the production of EVs through HIF-1α, enhancing Rab27a transcription in tumor B cells." (PMID 35563739, 2022). "However, we found that Rab27a-overexpressing MDA-MB-231 xenograft tumors grew significantly slower than control tumors, and the anticancer activity of BHMPS was only observed in Rab27a-overexpressing tumor xenografts." (PMID 35053535, 2022). "To determine whether tumor EV secretion plays an active role in macrophage-induced tumor cell invasion, we knocked down Rab27a, a known regulator of the EV secretion machinery." (PMID 34298673, 2021). "However, Rab27a and Rab27b have sometimes been reported to act as tumor suppressors, because they are downregulated in colorectal and prostate cancers and their lower levels of expression are correlated with worse outcomes." (PMID 34483204, 2021).
tumor (continued). "Inhibition of Rab27a led to a reduction in primary tumor growth and the number of lung metastases in a 4T1 cell (metastatic cell line) xenograft but not in a TS/A (non-metastatic) xenograft model, indicating a possible therapeutic use of Rab27 inhibition for reducing metastases." (PMID 34830787, 2021). "To determine whether tumor cell-released PTHrP-expressing EVs are critical for adipose tissue lipolysis and browning, we disrupted LLC release of EVs in vivo by knocking down the expression of Rab27A before tumor implantation." (PMID 33510128, 2021). "In addition to regulating tumor cells, Rab27a/b also participates in exosome exchange between different cells in the tumor microenvironment." (PMID 34141705, 2021). "The most profound effect of Rab27a knockdown was observed in livers, where both CD11b+Ly6C+Ly6G+ granulocytic cells; CD11b+Ly6C+Ly6G- monocytic cells and CD11b+Ly6C-Ly6G- macrophage populations were significantly decreased upon knockdown of Rab27a in the primary tumor." (PMID 32355248, 2020). "Furthermore, targeting Rab27a or TRAF3IP2 each reduced the potential of the tumor cells with the surrounding stroma, indicated by reduced growth of MSCs coinjected with MDAKDRab27a." (PMID 32483202, 2020). "Cheng and colleagues revealed that sEVs‐miR‐146a‐5p, a major miRNA expressed in cancer stem cells (CSCs) that depends on Rab27a activation, decreased the number of tumor‐infiltrating CD8+ T cells, thus promoting the formation of an immunosuppressive cancer microenvironment in CRC." (PMID 33377655, 2020). "Function of Rab27a in cancer has been previously linked to non-cell autonomous effects of downregulating EV production in controlling tumor growth and metastasis." (PMID 32355248, 2020). "Expression of Rab27a at the site of the primary tumor mediates not only changes in EV production, but regulates expression of multiple secreted factors associated with EMT processes and tumor remodeling." (PMID 32355248, 2020). "In addition to regulating tumor cell-intrinsic properties, Rab27A/B are also involved in the exchange of exosomes between different cells within the tumor microenvironment." (PMID 30925917, 2019). "In 4 T1 tumor models, the accumulation of exosomal PD-L1 in the tumor microenvironment induced immunotherapy resistance by suppressing the secretion of granzyme B. Notably, knockdown of Rab27a in tumor cells significantly enhanced the efficiency of anti-PD-1 therapy and inhibited 4 T1 tumor growth." (PMID 31647023, 2019). "RAB27A-mediated exosome secretion can promote tumor cell growth, tumor metastasis, and progression." (PMID 31511502, 2019). "The effects of Pd-l1, Rab27a, or nSMase2 null cells on the distant WT tumor were similar." (PMID 30951669, 2019). "In addition, Rab27A and Rab27B, the family members of Rab37, mediate exosomal pathways discarding tumor-suppressor microRNAs to enhance cancer progression." (PMID 30158579, 2018). "Exosomes collected from Rab27A-expressing cells promote tumor growth of Rab27A-knockdown cells and increase systemic accumulation of neutrophils, suggesting that Rab27A-dependent exosome secretion enhances the mobilization of neutrophils, thereby promoting tumor growth and metastasis." (PMID 30081925, 2018). "Further studies are needed to determine whether Rab27A/B-induced neutrophil recruitment is involved in enhancing the formation of the tumor-promoting microenvironment." (PMID 30081925, 2018). "Rab GTPases, including Rab27a and Rab27b, are the key regulators of exosomes secretion and Rab27 is closely related to the occurrence and the development of tumor, which indicates the role of exosomes secretion in tumor biology." (PMID 30217217, 2018). "Both Rab27A and Rab27B enhance cell proliferation and tumor development." (PMID 30081925, 2018). "In addition, among tumour samples, the staining intensity of Rab27a was increased in HCC with vascular invasion." (PMID 29725020, 2018).
tumor (continued). "There is a decrease in functional vasculature suggesting that Rab27A plays a tumor promoting role." (PMID 28146434, 2017). "Rab27A protein was mainly localized in the cytoplasmic compartment of tumor cells." (PMID 29088864, 2017). "Interestingly, silencing Rab27a by RNA interference disrupted exosome-dependent and -independent mechanisms that modify the tumor microenvironment and can also reduce tumor growth and metastasis." (PMID 28257101, 2017). "Recently, Rab27A was also reported to promote tumor progression." (PMID 27556511, 2016). "The Rab27A-expression sphere tumor grew more quickly than the control group (L.V.-luc)." (PMID 27556511, 2016). "Multivariate analysis further elucidated that Rab27A protein expression and tumor differentiation may identified as two independent prognostic factors for CRC prognosis in this present study." (PMID 26070933, 2015). "Moreover, multivariate analysis was executed and the results showed that Rab27A protein expression (p = 0.012) and tumor differentiation (p = 0.004) were two independent predictors of overall survival." (PMID 26070933, 2015). "According to univariate analysis, several factors were correlated with overall survival of 112 CRC patients, including Rab27A protein expression (p = 0.001), tumor differentiation (p = 0.001), serum CEA level (p = 0.006), T (p = 0.004), M (p = 0.005) and TNM stage (p = 0.003)." (PMID 26070933, 2015). "However, if the neutrophils were pre-treated with IFN-γ or TNF-α, T-sMs increased Rab27a expression in the neutrophils from tumor-bearing mice and pG/pI6-mice to the similar level of that in the neutrophils from naive mice." (PMID 25587026, 2014). "However, the other characteristics of Rab27a, especially its contribution to grade progression and tumor survival rate, make such strategies less appealing." (PMID 24587032, 2014). "Conversely, the tumor-promotional neutrophils recovered the expression of Rab27a and Trail, resumed the activation levels of PI3K and p38 MAPK pathways in response to stimuli, and expressed higher levels of IL-18 and NK-activating ligands such as RAE-1, MULT-1, and H60." (PMID 25587026, 2014). "Rab27a expression is frequently altered in many tumor types." (PMID 24587032, 2014). "We conducted univariate Cox regression analysis using clinical and genetic variables for the independent cohorts and observed that Rab27a expression, preoperative KPS score, tumor resection extent, and IDH1 mutation status were significantly associated with OS." (PMID 24587032, 2014). "Here, using Rab27a inhibition to modulate exosome secretion, we show the existence of at least 2 distinct populations of vesicles after purification by classical ultracentrifugation from mouse tumor cell conditioned medium." (PMID 24009879, 2012). "Moreover, Rab27a was shown to play an important role in the regulation of the tumor microenvironment as an essential protein for vesicle exocytosis and exosome release, while Rab27a expression levels correlate positively with a poor prognosis in cancer patients." (PMID 38715944, 2024). "This statement is supported by the fact that alteration of the expression of Rab27a and Rab27b proteins, involved in the transport of late endosomal/lysosomal-like compartments to the plasma membrane in the exosomal pathway, result in an alteration of the tumor-cell-derived exosomes tumoral effect." (PMID 36986603, 2023). "Contrary to our expectations, we observed an increase in the initial seeding capacity of GFP-shRab27a-KPC cells regardless of whether the primary tumor was proficient or deficient in Rab27a expression." (PMID 32355248, 2020). "In addition, GFP-scr-KPC cells generated more metastases even in the context of Rab27a deficient primary tumors, suggesting that Rab27a-mediated primary tumor-induced myeloid expansion is not required for metastatic outgrowth." (PMID 32355248, 2020).
tumor (continued). "However, Rab27a knockdown cells had an unexpected advantage at initial steps of metastatic seeding, suggesting that Rab27a may alter cell-autonomous invasive properties of the tumor cells." (PMID 32355248, 2020). "Therefore, deletion of either nSMase2 or Rab27a completely inhibits tumor growth." (PMID 33178688, 2020). "However, several reports indicates Rab27A as a tumor suppressor." (PMID 29088864, 2017). "Both the deletion of Rab27a and the inhibition of nSMase2 (using GW4869) in the mouse model of drug-resistant breast cancer can effectively suppress tumor growth, surpassing the inhibitory impact of the anti-PD-L1 antibody at 30 and 60 units." (PMID 38562933, 2024). "Results show that Rab27A is overexpressed in NSCLC, and regulates the tumor proliferation, migration, invasion, and cell motility in vitro and in vivo, and is negatively regulated by miR-124." (PMID 38521810, 2024). "Tumor cells are more likely to release exosomes in the hypoxic TME, which is related to the activation of the small GTPase Rab27a, a major regulator of exosomal synthesis, regulated by HIF-1α." (PMID 36899389, 2023). "The inhibition of exosome secretion or uptake via the knockdown of RAB27A, a regulator of exosome secretion, reduces the expression of CD47 in tumour cells, promotes phagocytosis by M1 macrophages in tumour tissues, and suppresses tumour progression." (PMID 36298556, 2022). "Expression of shRNAs for Rab27a in human BM1 and mouse LMB tumor cells decreased EV secretion by ~50% (measured by NTA), similar to previous reports." (PMID 34298673, 2021). "Lower concentrations of CD73+ TDEVs and adenosine were detected in the CSF and blood of nSMase2−/−, Rab27a−/− and CD73−/− GL-261 tumour-bearing mice than in those of WT GL-261 tumour-bearing mice." (PMID 34753903, 2021). "RAB27A, RAB27B, and RAB35 are abnormally expressed in tumors and participate in the regulation of tumor exosome secretion." (PMID 34088337, 2021). "In a Rab27a knockout CRC model, PD‐L1+ sEVs appeared to inhibit T‐cell activity to promote tumor growth and resist to immune checkpoint protein inhibitors." (PMID 33377655, 2020). "Among 15 genes in the signature, except four genes, RAB27A, ADGRB1, MT1F, and TPT1, the remaining were differentially expressed between tumor and normal tissues." (PMID 33329725, 2020). "To understand if modulation of Rab27a expression also affects primary tumor growth, we orthotopically injected scr-KPC and shRab27a-KPC cells and measured tumor growth 2 weeks after injection." (PMID 32355248, 2020). "Reduced expression of Rab27a resulted in decreased sEV production, and in decreased release of pro-angiogenic factors (PlGF-2, osteopontin, and PDGF-AA) from tumor cells, interfering with BMDC mobilization and tumor invasiveness." (PMID 32709086, 2020). "MiR-582-5p has tumor-suppressive functions and reduces the tumor cell proliferation and migration via targeting CDK1, FOXC1, and RAB27a." (PMID 33183321, 2020). "Especially, the small GTPases, RAB27A and RAB27B, were participated in exosome secretion in various human tumor cells." (PMID 31402975, 2019). "We first examined Rab27a expression in 20 cases of HCC and matched non-tumour tissues by Western blot and another 11 pairs by real-time quantitative RT-PCR (qRT-PCR)." (PMID 29725020, 2018). "For example, MES GBMs (red arrows) were enriched for CAV1, CD44, CD63, RAB27A, SDCBP and SMPDL3A, while PN (blue arrows) tumours contained higher levels of transcripts for ANXA6, CD81, hnRNPA2B1, YBX1 (RNA binding proteins) and RAB35." (PMID 30034643, 2018). "To better imitate the microenvironment of HCC cells in the liver and determine the effect of decreased exosome secretion by Rab27a downregulation on intrahepatic metastasis of HCC cells, we established orthotopic xenografts of HCC tumours." (PMID 29725020, 2018). "Most importantly, knockdown of Rab27a in melanoma cells has been shown to decrease EXO production and inhibit tumor growth and metastasis in mice." (PMID 29760691, 2018).
tumor (continued). "In some tumor cells, however, exosome release depends on the Rab GTPase family, whose members, such as RAB11, RAB27A, and RAB31, are important regulators of membrane trafficking." (PMID 28257101, 2017). "Relatively, other clinical items, such as gender, age, tumor size and location, histological type and tumor differentiation, serum CEA level and N, were rarely correlated with high Rab27A protein expression." (PMID 26070933, 2015). "We have thus recently demonstrated a role of the small GTPases RAB27A and RAB27B in exosome secretion by a human tumor cell line." (PMID 24009879, 2012). "Targeting EV biogenesis or sorting mechanisms such as Rab27A inhibition or the interactions between CD63, LAMB1 and CD147 could provide novel therapeutic avenues to reverse resistance and re‐sensitize tumours to GCB." (PMID 41159684, 2025). "Tumor growth was not impaired with Rab27a or Rab35 KO cells, and overall cell proliferation, as stained for by Ki-67 was unchanged." (PMID 41137505, 2025). "We found that the transcript level of Rab27b but not Rab27a was increased in tumor tissues compared with adjacent normal tissues, whereas the protein levels of both Rab27a and Rab27b were increased in tumor tissues." (PMID 40360476, 2025). "Hypoxic conditions upregulate the expression of Rab27a in B cells and promote the release of CD19+ extracellular vesicles, which generate immunosuppressive adenosine from treated tumours through the CD39/CD73 pathway, ultimately impairing the function of CD8+ T cells." (PMID 38997802, 2024). "Previous studies have found that inhibition of exosome secretion by deletion of exosome secretion regulator Rab27a or NSMASE2, or treatment with exosome secretion inhibitor GW4869, significantly restrain tumour growth and augment the efficacy of immunotherapy in vivo." (PMID 37700095, 2023). "In addition, down-regulation of Rab27a can increase the expression of genes related to the EMT pathway and alter the characteristics of autonomous invasion of tumor cells." (PMID 35965504, 2022). "And these reveal that Rab27a can play divergent roles in regulating pro-metastatic propensity of PDAC cells: by generating pre-metastatic environment at the distant organ sites, and by suppressing invasive properties of the tumor cells." (PMID 35965504, 2022). "The role of EVs was confirmed by knockdown of Rab27a/b via a short hairpin RNA lentivirus in the brain parenchyma, which decreased the release of EVs, reduced the down regulation of PTEN and subsequently decreased metastases and tumor growth in the brain." (PMID 34298912, 2021). "Expectedly, knock-down of Rab27a and Rab27b potently inhibited exosome release from tumor cells without remarkably changing viabilities of the tumor cells." (PMID 34229732, 2021). "We showed that targeting Rab27a decreases exosome release and delays progression of tumor growth, but fails to affect micrometastasis." (PMID 32483202, 2020). "Overall, our work identified that the GTPase Rab27a functions in both a cell-autonomous as well as a non-cell-autonomous fashion to affect tumor progression." (PMID 32355248, 2020). "Using a combination model of experimental liver metastasis and primary tumor seeding, we demonstrated that Rab27a has both a cell-autonomous and non-cell autonomous role in modulation of the immune niche and metastatic outgrowth." (PMID 32355248, 2020). "Supporting our in vitro data, the in vivo data demonstrate that silencing Rab27a delays tumor development but not micrometastasis." (PMID 32483202, 2020). "In vivo, tumor growth and overall survival was not affected by knockdown of Rab27a, but lower Ki-67 expression was observed at the tumor border." (PMID 33282910, 2020). "In contrast, all mice injected with Rab27a null or Pd-l1 null TRAMP-C2 cells showed no tumor growth during the same time period." (PMID 30951669, 2019).